CTLA4 (cytotoxic T-lymphocyte associated protein 4)
Diseases named in the same sentence as CTLA4 in open-access papers (continued):
Sharing a sentence is not in itself a finding about the gene and the disease.
cancer (continued). "With the development of cancer immunotherapy, therapeutic aptamers have been reported for targeting immune checkpoints, including CTLA-4, PD-1, and PD-L1." (PMID 38762484, 2024). "Agents that inhibit both the PD-1/PD-L1 and CTLA-4 pathways have received approval for the treatment of multiple cancer types." (PMID 39926600, 2024). "Anti-CTLA4 monoclonal antibodies, including tremelimumab and ipilimumab, have been used alone or in combination with other cancer therapies like radiotherapy, anti-cancer vaccines, or chemotherapy." (PMID 38418707, 2024). "Checkpoint inhibitors, including programmed cell death protein 1 (PD-1), programmed cell death-ligand 1 (PD-L1), and cytotoxic T-lymphocyte-associated protein 4 (CTLA-4) inhibitors, have remarkably succeeded in clinical trials across various cancer types." (PMID 38690455, 2024). "With the approval of immune checkpoint inhibitors targeting PD-L/CTLA-4, overall survival has improved for many cancers." (PMID 39023752, 2024). "Along with the cytotoxic T-lymphocyte-associated protein 4 (CTLA-4) pathway, this pathway is a crucial target for novel cancer therapeutics, including the monoclonal antibodies (mAbs), peptides, and patented small molecules." (PMID 39001358, 2024). "This same study also showed that levels of sBTLA remained constant in patients with a variety of cancers who were treated with anti-PD-1, combination therapy (of anti-PD-1 plus anti-CTLA4) or other ICI." (PMID 38822401, 2024). "Impressive results in a subset of cancers have been obtained using immunotherapies including anti-CTLA4, anti-PD-1, and anti-PD-L1 or chimeric antigen receptor (CAR) T cell therapies." (PMID 38449858, 2024). "Despite growing clinical applications of anti-CTLA-4 antibodies for the treatment of cancer, its precise mechanisms of action remain poorly defined." (PMID 38053333, 2024). "Humans or mice that lack PD-1 or CTLA-4 exhibit a global autoimmune diathesis that corresponds to the toxicities observed when these structures are targeted in immunotherapy of cancer." (PMID 39840036, 2024). "The Food and Drug Administration (FDA) has approved ICIs designed to target CTLA-4 as a treatment option for various cancer types." (PMID 39143529, 2024). "The stabilization of CTLA4 expression by Foxp3, in turn, amplifies the attenuation of T-cell response in the context of cancer." (PMID 38617537, 2024). "Among various types of immune checkpoints, two receptor classes are actively expressed on activated T cells, CTLA-4 and PD-1, which are targeted by cancer cells to negatively regulate the T cells’ function from killing the tumors." (PMID 38255322, 2024). "According to the most current research data, the HIF-1 inhibitor echinomycin enhanced the anti-CTLA-4 treatment’s cancer immunotherapy effectiveness, with efficacy comparable to anti-CTLA-4 + anti-PD-1 antibodies." (PMID 38165484, 2024). "Blocking these PD‐1/PD‐L1 and CTLA‐4/B7 axes has led to improved overall survival and increased response rates in diverse cancer types." (PMID 38594879, 2024). "Further, NMUR1 was positively associated with a spectrum of immune cells, notably CD8+ T cells and NK cells, and immune inhibitors such as PDCD1 and CTLA4, across diverse cancers." (PMID 39055918, 2024). "Since then, anti-PD-L1, anti-PD-1, and anti-CTLA4 antibodies have become widespread as cancer therapeutic agents and are utilized across multiple cancer types." (PMID 38822401, 2024). "These inhibitors target proteins such as PD-1, PD-L1, and CTLA-4, enhancing the immune system’s ability to fight cancer." (PMID 39769334, 2024). "The discovery of anti-PD-1/PD-L1 and anti-CTLA-4 has led to definite changes in the field of cancer immunotherapy." (PMID 38756774, 2024). "In conclusion, although the combination of CTLA-4 and PD-1 inhibitors offers a powerful tool in cancer immunotherapy, it also presents significant challenges that require careful consideration and management." (PMID 39335671, 2024).
cancer (continued). "A combination therapy involving anti-CTLA-4 and anti-PD-1 inhibitors is also proposed in metastatic cancer, with dosage and duration varying depending on the cancer type." (PMID 38675461, 2024). "The Rothlin–Ghosh group tried several subcutaneously implanted cancer models, including the CTLA-4 and PD-1 checkpoint inhibitor-resistant YUMM1.7 and an orthotopic glioblastoma model in these mice." (PMID 38791338, 2024). "Our findings suggest potential immunotherapeutic interventions for high-risk precursor lesions, namely, targeting PD-1/PD-L1 in IPMN and CTLA-4-positive Tregs in PanIN to restore immunosurveillance and prevent progression to cancer." (PMID 38474199, 2024). "An increase in plasma CTLA-4, a potent inhibitory checkpoint molecule, is a general phenomenon in cancer, and its transcripts have been detected in lymph nodes and in the spleen but not in non-lymphoid tissue." (PMID 38793771, 2024). "The promising strategy includes targeting the HLA-G/ILT signaling pathway alongside the use of CTLA-4/B7 and PD-1/PD-L1 as new immune checkpoints in cancer development." (PMID 39594832, 2024). "Combining IL-15 with anti-CTLA-4 and anti-PD-L1 antibodies demonstrated highly effective antitumor effects in several cancer models." (PMID 39507777, 2024). "Cancer immunotherapy clinical trials reported that mAbs against CTLA-4 have established unprecedented therapeutic advantages and generated a long-term durable immune response in multiple types of advanced cancers." (PMID 38255322, 2024). "Using ICI in the form of antibodies that bind these receptors and block the binding of their cognate ligands from cancer cells has shown a clear impact in T-cell immunotherapies, especially for PD-1 and CTLA-4." (PMID 39511139, 2024). "Dual ICIs such as tremelimumab plus durvalumab and nivolumab plus ipilimumab target proteins named PD-1 and CTLA-4 on T cells, respectively, helping to activate them to identify and attack cancer cells." (PMID 39399471, 2024). "CTLA-4 and PD-1 have been identified as crucial regulators of T-cell reactions and exhibit promising potential as therapeutic targets for cancer treatment." (PMID 39170916, 2024). "These pathways, such as programmed cell death protein 1 (PD-1)/programmed cell death 1 ligand 1 (PD-L1) and cytotoxic T-lymphocyte-associated protein 4 (CTLA-4), play a role in immunosuppression and evasion of the immune system by malignant tumors." (PMID 38774326, 2024). "Over the years, CTLA-4 inhibitors, such as ipilimumab, have been developed to block this protein and enhance the immune response against cancer cells." (PMID 39685500, 2024). "Immune checkpoint inhibitor therapy targeting PD-1, PD-L1 and CTLA-4 has been approved for multiple cancer therapies." (PMID 39767559, 2024). "Cancer immunotherapy has advanced rapidly with the inclusion of numerous ICBs approved against specific targets, such as ipilimumab, an inhibitor of CTLA-4, and nivolumab and pembrolizumab, PD-1 inhibitors." (PMID 38785930, 2024). "The primary finding and thorough investigation have concentrated on CTLA4 and PD-L1/PD-1; the treatment of different cancers with immunotherapy frequently includes the combined utilization of anti-PD-1/PD-L1 and anti-CTLA-4." (PMID 38451188, 2024). "ICIs have transformed cancer treatment by targeting proteins like PD-1 and CTLA-4, which cancer cells exploit to suppress the immune response." (PMID 39518676, 2024). "CCL22 can be induced by cancer cell-derived IL-1α and the downstream recruitment of Tregs leads to a downregulation of the cell-surface antigen CTLA-4." (PMID 38928238, 2024). "Nevertheless, a portion of cancer patients still show low responsiveness to treatments targeting PD-1 and CTLA4, which has also promoted the exploration of the next generation of inhibitory receptors." (PMID 39342365, 2024). "Simultaneously, there has been a significant surge in academic articles PD-1 and CTLA-4 in cancer research." (PMID 38390331, 2024).
cancer (continued). "There is a notable increase in CTLA-4 expression within cancer cells, accompanied by elevated Treg expression in the adjacent TME, which helps these cells evade immune surveillance." (PMID 38791528, 2024). "For example, Yervoy (Ipilimumab) manufactured by Bristol-Myers Squibb is the world’s first approved and marketed CTLA-4 antibody drug, which has been used for the treatment of a variety of cancers." (PMID 39474352, 2024). "In recent years, the blockade of CTLA-4 has been investigated as a cancer immunotherapy approach, and has been a target for immune checkpoint inhibitors." (PMID 38418707, 2024). "To evaluate the possible association between Al accumulation and the immune escape ability of cancer cells, we correlated data from RNA-seq concerning CTLA4, PDL1, and PD1 and the Al amount found in the corresponding samples." (PMID 39769153, 2024). "We discovered that JAK2-mutated cancers displayed upregulated expression of immune checkpoint molecules (such as PDCD1, CD274, CTLA4, and TIGIT) compared with JAK2-wild tumors." (PMID 38200372, 2024). "In contrast, butyric acid has immunosuppressive effects and has been reported to increase tolerance to CTLA-4 blockade and the percentage of regulatory T cells (Tregs) in the cancer immune system." (PMID 38280026, 2024). "Within the last decade, immunotherapy has emerged as a new pillar of cancer therapy with the success of immune checkpoint inhibitors that inhibit CTLA-4, PD-1, and PD-L1." (PMID 39683778, 2024). "Immune checkpoint therapy has revolutionized cancer treatment, and antibodies targeting PD‐1, PD‐L1, and CTLA‐4 are successfully used to combat a wide variety of cancers." (PMID 39560030, 2024). "Lately, the realm of immune intervention techniques focused on immune checkpoint molecules like PD-1 and cytotoxic t-lymphocyte associated antigen 4 (CTLA4) has offered fresh hope for treating associated disorders, especially cancer." (PMID 38420194, 2024). "Employing anti-PD-1/PD-L1 and anti-CTLA-4 drugs targets different stages of the cancer immunity cycle; their combined use can produce a synergistic effect, helping to overcome resistance to monotherapy." (PMID 39726592, 2024). "Immune checkpoint inhibitors such as ipilimumab (anti-CTLA-4 antibody) or pembrolizumab (anti-PD-1) have attracted the most attention due to their application to a wide variety of cancer types, with substantial benefit to 20% of treated patients." (PMID 38256021, 2024). "This represents a significant advancement in cancer immunotherapy, offering distinct benefits by selectively targeting CTLA4 on PD-1 + T cells." (PMID 38475778, 2024). "The discovery and clinical application of immune checkpoint inhibitors targeting CTLA4 and PD-L1 have revolutionized cancer therapy." (PMID 38649961, 2024). "Ipilimumab, an anti-CTLA-4 monoclonal antibody, acts on the immunological checkpoint protein CTLA-4, enhancing T cell activation and facilitating an immune response against cancer cells." (PMID 38931856, 2024). "It has been demonstrated that antibodies targeting CTLA‐4 increase survival rates in a large number of malignant tumor individuals, especially those with NSCLC." (PMID 38571678, 2024). "In this review article, we provide a comprehensive survey of the biological mechanisms of ICPs that are most frequently targeted in cancer therapy, including CTLA-4, PD-1, PDL-1, and LAG3." (PMID 39359534, 2024). "At present, the ICIs permitted by the FDA to treat cancer mainly target cytotoxic T-lymphocyte antigen 4 (CTLA-4), programmed cell death protein 1 (PD-1), and PD-ligand 1 (L1)." (PMID 38817600, 2024). "The discovery and development of specific inhibitors for immune checkpoints, including CTLA-4 and programmed cell death protein 1 (PD-1), have revolutionized cancer immunotherapy." (PMID 39671359, 2024). "T. Honjo and J. Allison discovered the important role of PD-1 and CTLA-4 inhibition in cancer therapy." (PMID 38893211, 2024).
cancer (continued). "Tumors can acquire an immunosuppressive phenotype through the expression of PDL1, CTLA4, and other immunosuppressive proteins to suppress innate and adaptive immune function, leading to immune escape of cancer cells." (PMID 38898490, 2024). "By blocking the PD-1/PD-L1 and CTLA-4 pathways, these drugs lift the immune “brakes,” allowing T cells to mount a more robust attack against cancer cells." (PMID 39518676, 2024). "The findings from The Cancer Immunome Atlas (TCIA) align with this correlation, demonstrating that when at least one of CTLA-4 or PD-1 is positive, high expression of EVI2A is associated with increased sensitivity to immunotherapy." (PMID 39449801, 2024). "Ipilimumab binds to CTLA-4, blocking its action on immune cells, therefore, allowing immune cells to target proliferating cancer cells." (PMID 38406102, 2024). "The findings offer insights into the molecular processes through which SCFAs modulate immune responses, emphasizing their potential as regulators of therapeutic outcomes in cancer patients undergoing CTLA-4 inhibition." (PMID 39351241, 2024). "Research has shown that persistent CTLA-4 expression in neoplastic cells from cancer patients can contribute to disease progression." (PMID 39194710, 2024). "Cancer regimens with anti-CTLA-4 monotherapy have largely been replaced by the combination of anti-CTLA-4 and anti-PD-1/PD-L1 antibodies." (PMID 38312352, 2024). "Poly (ADP-ribose) polymerase inhibitors (PARPi) and immune checkpoint inhibitors, including monoclonal antibodies targeting PD-1 and CTLA-4, have transformed cancer therapy." (PMID 39724285, 2024). "The use of immune checkpoint inhibitors (ICIs) targeting PD-1, PD-L1, and CTLA-4 has become a promising treatment strategy for various types of cancer." (PMID 37713112, 2024). "In September 2023, eleven anti-PD-1/PD-L1/CTLA-4 mAbs have been approved in US and/or EU for the treatment of different cancers." (PMID 38318190, 2024). "Antibodies that target immune checkpoints such as cytotoxic T lymphocyte antigen 4 (CTLA-4), programmed cell death protein/ligand 1 (PD-1/PD-L1) are approved for treatment of multiple cancer types." (PMID 39343508, 2024). "Given its role in regulating the immune system, CTLA-4 has become an important target for cancer immunotherapy." (PMID 39343796, 2024). "The US FDA has licensed three separate classes of CPIs to treat distinct cancers, namely CTLA-4 inhibitors (Ipilimumab), PDL-1 inhibitors (Avelumab, Durvalumab, and Atezolimumab), and PD-1 inhibitors (Cemiplimab, Pembrolizumab, and Nivolumab)." (PMID 38165484, 2024). "Proteins such as PD-L1 and CTLA-4 are critical to the immunosuppressive mechanisms of cancer, which allow cancer cells to escape the body’s immune response." (PMID 39685591, 2024). "The application of ICIs in targeting PD-1/PD-L1 or CTLA-4 has brought about a groundbreaking transformation in cancer therapy." (PMID 38482205, 2024). "By blocking proteins like PD-1, PD-L1, and CTLA-4, these drugs enable a stronger and more sustained immune response, leading to the destruction of cancer cells." (PMID 39273605, 2024). "An increasing number of immune checkpoint inhibitors, including monoclonal anti-CTLA-4, anti-PD-1, and anti-PD-L1 antibodies, have been shown to be effective in the treatment of cancers." (PMID 39534095, 2024). "This was further demonstrated by the suppression of CSN5-mediated reduction in PD-L-1 expression in cancer cells, which increased the reactivity of the cells to anti-CTLA4 treatment." (PMID 38660299, 2024). "Here, we performed deep shotgun metagenomic sequencing of baseline fecal samples from patients on the CA209-538 clinical trial of ipilimumab (anti-CTLA-4) and nivolumab (anti-PD-1) for 106 patients with diverse rare cancers (our discovery cohort)." (PMID 38429524, 2024). "Immune checkpoint blockade, targeting CTLA4, PD-1, and PD-L1 which was previously effective in cancers, such as melanoma, holds promise for recurrent GBM." (PMID 39367418, 2024).
cancer (continued). "Several investigations have been conducted on the use of PD-1 in conjunction with CTLA-4 for cancer therapy; however, the outcomes have been unsatisfactory according to studies." (PMID 38305808, 2024). "The researchers observed good therapeutic efficacy after administering AK104 (a PD-1/CTLA-4 BSAB) in combination with XELOX (capecitabine plus oxaliplatin) or modified XELOX in patients with unresectable advanced G/GEJ cancer." (PMID 38627681, 2024). "Inhibition of PD-1, PD-L1, or CTLA-4 can relieve the brakes on the immune system, allowing T cells to recognize and attack cancer cells effectively." (PMID 39329702, 2024). "Immunotherapy for cancer is a strategy to fight against the disease, including approaches like immune checkpoint therapies targeting CTLA-4 and PD-1, along with adoptive T cell therapies such as chimeric antigen receptor T-cell (CAR-T) therapy." (PMID 39767682, 2024). "To date, several in vivo studies have shown the effectiveness of VISTA-targeted drugs in combination with PD-1/PD-L1 or CTLA-4 inhibitors, although their effectiveness varies among drug combinations and cancer types." (PMID 38503143, 2024). "The introduction of immune checkpoint inhibitors (ICIs), i.e., anti-PD-1, anti-PD-L1, and anti-CTLA-4 antibodies, has revolutionized cancer treatment, providing unprecedented survival in some patients." (PMID 38835768, 2024). "Given the roles of PD-1/PD-L1 and CTLA-4 in the Cancer-Immunity Cycle, CTLA-4 inhibitors initiates T cell activation, whereas PD-1/PD-L1 inhibitors are involved in the reactivation of effector responses in later stages." (PMID 39068460, 2024). "Favorable clinical outcomes have been reported for various cancers treated with antibodies targeting PD-1, PD-L1, and cytotoxic T-lymphocyte-associated protein 4 (CTLA-4), prompting increased interest in cancer immunology." (PMID 39769351, 2024). "Identifying immune checkpoints, including PD-1, PD-L1, and CTLA-4, is pivotal in advancing cancer immunotherapy." (PMID 38531930, 2024). "Anti-CTLA-4 plus anti-PD(L)-1 is the only combination to date that has shown better survival in patients with MSI-H cancers." (PMID 39238638, 2024). "More research is also needed to understand why the patient’s cancer recurred despite decreases in the expression levels of PD-L1 and CTLA-4." (PMID 38474377, 2024). "The results demonstrated that a robust correlation exists between VISTA and CTLA-4, which suggests its potential role in cancer development and progression." (PMID 38357542, 2024). "Immunotherapeutics targeting PD-1, PD-L1, and CTLA-4 have transformed cancer care, but only a small minority of patients with cancer respond to these lifesaving treatments." (PMID 38837964, 2024). "ICIs, encompassing inhibitors targeting PD‐1, PD‐L1, and cytotoxic T‐lymphocyte antigen‐4 (CTLA‐4), have demonstrated unprecedented efficacy in treating numerous cancers." (PMID 38594879, 2024). "So targeting CD39, CD73, and adenosine receptors in the presence of immune checkpoint therapy (anti-PDL1/PD1; ANTI CTLA-4) can prove to be a novel immunotherapeutic strategy against immune-resistant cancer cells." (PMID 38347575, 2024). "The subsequent development of immuno-oncology with the introduction of antibodies against PD-1 (nivolumab, pembrolizumab), PD-L1 (atezolizumab, durvalumab, and avelumab), and CTLA4 (ipilimumab) has led to a paradigm shift in the treatment of cancer." (PMID 39606229, 2024). "TIDE has the potential to forecast the result of cancer patients who undergo treatment with initial anti-PD1 or anti-CTLA4 medications." (PMID 38601163, 2024). "ICIs such as anti-CTLA-4, anti-PD-1, and anti-PD-L1 can bind to these co-inhibitory receptors, effectively reviving the anti-cancer immune response." (PMID 38893120, 2024). "Immunotherapy has changed the traditional model of cancer treatment via the application of PD-1/PD-L1 and CTLA4 in many cancer patients." (PMID 38302980, 2024).